HP (haptoglobin)
Diseases named in the same sentence as HP in open-access papers (continued):
Sharing a sentence is not in itself a finding about the gene and the disease.
prostate carcinoma (16 papers, 2009 to 2026). A carcinoma that arises from epithelial cells of the prostate gland. "High expression of FUT8 and haptoglobin was observed in prostate cancer cell lines, and serum levels of fucosylated haptoglobin were associated with high-grade prostate cancer." (PMID 34948129, 2021). "Several studies have reported abnormal fucosylation in colorectal and prostate cancer types and increase in haptoglobin decorated with glycan of core fucosylation (α-1-6 linked fucose on N-acetylglucosamine at the reducing end) in serum samples of PC patients." (PMID 34199928, 2021). "Analysis of fucosylation of serum haptoglobin showed that core-type fucosylation is more characteristic in prostate cancer than in gastrointestinal cancer." (PMID 34948129, 2021). "It is concluded that the expression of haptoglobin is correlated with the occurrence of prostate cancer and bone metastasis, which is consistent with previous reports." (PMID 31413735, 2019). "Haptoglobin was also expressed in prostate cancer epithelial cells, with positive expression in nucleus and cytoplasm." (PMID 31413735, 2019). "It has been verified that CD59, haptoglobin and tetranectin are prostate cancer bone metastasis related proteins." (PMID 31413735, 2019). "This indicates that the expression of haptoglobin in prostate cancer cells is influenced by the microenvironment in different metastatic sites." (PMID 31413735, 2019). "CD59 and haptoglobin were up-regulated in prostate cancer with bone metastasis while tetranectin was down-regulated." (PMID 31413735, 2019). "In the other original study on prostate cancer, the expression levels of 35 genes including HP and LCN2 were found to be correlated with overall survival (OS)." (PMID 28771541, 2017). "Thus, the data were distinct from that obtained with haptoglobin, wherein SNA‐1 bound to the haptoglobin in the prostate cancer group with an affinity that was higher than its affinity for binding to the haptoglobin of either the BPD group or the normal control group 22." (PMID 26880719, 2016). "A proteomic analysis of the urine revealed APPs (FGA, FGG, HP, ITI4, SERPINA1) as biomarkers for prostate cancer, but the paper lacks the analysis of their pathophysiological role." (PMID 35328392, 2022). "Subsequent analyses by this group revealed that an increase in the RM2 reactivity to haptoglobin, a representative of the acute phase proteins (APP), is a key determinant for more specific and sensitive diagnoses of early‐stage prostate cancer." (PMID 26880719, 2016). "Haptoglobin can be imaged with iodinated RM2-mab, originally developed for prostate cancer imaging." (PMID 37957176, 2023). "In this study, we confirmed that the expression of haptoglobin was significantly higher in prostate cancer (with or without bone metastasis) and bone metastasis tissues than in prostate hyperplasia." (PMID 31413735, 2019). "The intensity of haptoglobin expression in bone metastatic tumor was significantly higher than that in prostate cancer tissue with or without bone metastasis." (PMID 31413735, 2019). "Tetranectin showed differential expression in epithelial and stromal cells of prostate cancer and hyperplasia tissues.The expression of CD59 was highest in PC3 and lowest in LNCap, while the expression of haptoglobin and tetranectin was the highest in DU145 and lowest in PC3." (PMID 31413735, 2019). "By mass spectrometry and ELISA analyses, we found that the serum level of haptoglobin in prostate cancer with bone metastasis and non-metastasis groups were significantly different." (PMID 31413735, 2019). "In the previous studies on serum haptoglobin in prostate cancer 17, 22, we frequently noticed that some lectins, including AAL and WGA, strongly recognized a ~50 kDa band of sera from patients with prostate cancer as well as BPD in lectin blotting." (PMID 26880719, 2016).
prostate carcinoma (continued). "In a recent study, 2-D DIGE gel electrophoresis coupled with MS and bioinformatics analysis identified serotransferrin (TF), alpha-1-microglobulin/bikunin precursor (AMPB) and haptoglobin (α-chain) (HP) as new urinary biomarkers, which could distinguish between BPH and prostate cancer." (PMID 30197761, 2018).
Cirrhosis (15 papers, 2006 to 2024). A chronic disorder of the liver in which liver tissue becomes scarred and is partially replaced by regenerative nodules and fibrotic tissue resulting in loss of liver function. "The main results were that, in the rats with cirrhosis, LPS caused high mortality and increased serum of α1AGP and of haptoglobin, and also of mRNAs of acute phase proteins to a level as found in the control animals." (PMID 16968543, 2006). "In particular, increased site-specific fucosylation, sialylation and isomeric glycan composition of haptoglobin differentiated better between cirrhosis and early NASH, with further improvements in AUC when combined with AFP compared with AFP alone." (PMID 37920152, 2023). "A targeted PRM approach was applied for the quantitation of the intact N-glycopeptides of serum haptoglobin, to characterize the alterations in site-specific glycopeptide forms between cirrhosis and HCC." (PMID 34436504, 2021). "This study confirmed that site-specific glycoproteomic analysis is an important tool to evaluate serum haptoglobin changes between cirrhosis and HCC samples." (PMID 34436504, 2021). "The glycosylation of serum haptoglobin has shown to have significant differences between cirrhosis and HCC, thus can be used for diagnosis." (PMID 34436504, 2021). "The results observed in the PCA plots, heat maps, and pie graphs showed consistent glycosylation differences in serum haptoglobin between the cirrhosis and HCC samples." (PMID 34436504, 2021). "We were able to identify site-specific glycosylation changes in serum haptoglobin that was extracted from patients with NASH cirrhosis and NASH-related HCC, where these changes were strongly related to the development of N-glycopeptide isomeric structures." (PMID 34436504, 2021). "A more recent paper showed increased hyperfucosylated glycans on haptoglobin in HCC as well as in cirrhosis." (PMID 32557671, 2020). "Another study showed that beta chain of haptoglobin decrease in the plasma of cirrhosis based on HCV." (PMID 33585012, 2020). "Limitations in the interpretation of the presented data are that the animals with cirrhosis already exhibited increased production of α1AGP and haptoglobin and that the data were obtained only from the group of survivors." (PMID 16968543, 2006). "The increase of α1AGP and haptoglobin in serum as well as of the mRNA of the later by BDL shows that this cirrhosis model in itself induced an acute phase response, probably because of the active fibrogenesis acting as an inflammatory process." (PMID 16968543, 2006). "The mRNAs of these proteins were increased by LPS (2-way ANOVA, P < 0.001) and only the mRNA of haptoglobin increased also by cirrhosis (2-way ANOVA, P < 0.001)." (PMID 16968543, 2006). "Twenty-four hours after LPS, the serum concentration of α1AGP and haptoglobin, the mRNA level of these acute phase proteins and of α2-macroglobulin and thiostatin rose to the same level in the animals with cirrhosis and in controls." (PMID 16968543, 2006). "For both α1AGP and haptoglobin, the interaction found between LPS and cirrhosis (2-way ANOVA, P < 0.001) decreased their serum concentrations." (PMID 16968543, 2006). "While focused primarily on cases with the highest number of DEPs like apolipoprotein A-I, haptoglobin, and fibrinogen alpha, several other liver proteins with fewer DEPs could still help distinguish different stages of cirrhosis." (PMID 39521382, 2024). "As such, future investigations should elucidate the importance of this PTM in the setting of cirrhosis as it may impact the production of and function of mature haptoglobin proteins in patients with more severe diseases." (PMID 39521382, 2024). "Moreover, by applying our LC-PRM-MS strategy, we were able to identify single and groups of haptoglobin N-glycopeptides that have potential to differentiate between patients with NASH cirrhosis and NASH-related HCC." (PMID 34436504, 2021).
Cirrhosis (continued). "In recent years, glycomic studies of serum haptoglobin have identified important isomeric structures, most of them being sialylated fucosylated glycans, with significant differences in abundance between patients with cirrhosis and HCC." (PMID 34436504, 2021). "Haptoglobin was extracted from serum samples of patients with NASH cirrhosis and NASH-related HCC." (PMID 34436504, 2021). "Haptoglobin is one of the deregulated serum proteins detected in advanced HCV- cirrhosis." (PMID 33585012, 2020). "The decrease of haptoglobin in serum cirrhosis patients has also been reported." (PMID 33585012, 2020). "Moreover, HP was shown to be elevated in liver cancer and decreased in cirrhosis." (PMID 39286634, 2024). "According to these studies, glycoproteomic analysis, focused on an extensive determination of isomeric N-glycopeptide structures, could increase the possibility of finding haptoglobin site-specific N-glycopeptides that can differentiate between cirrhosis and the early stages of HCC." (PMID 34436504, 2021). "Furthermore, that the BDL cirrhosis model itself triggered the synthesis of α1AGP and haptoglobin." (PMID 16968543, 2006). "Of significance, the statistical analysis of the data found seven haptoglobin N-glycopeptides that can be used alone, combined with AFP, or combined themselves, to better differentiate between cirrhosis and HCC group samples than previous approaches." (PMID 34436504, 2021). "In this study, we revealed the site-specific microheterogeneity (isomeric composition) of serum haptoglobin, and demonstrated that the developed isomeric N-glycopeptides can be used to differentiate NASH cirrhosis and NASH-related HCC." (PMID 34436504, 2021). "We have previously observed the differential expression of some HP isoforms between HBV-HCC and HBV-cirrhosis." (PMID 24066001, 2013). "Recent studies on fucosylated glycoforms of other liver-secreted proteins, namely haptoglobin, kininogen, α1-antitrypsin and Golgi protein 73 have shown the promising potential of these glycobiomarkers for differential diagnosis of HCC versus cirrhosis with improved sensitivity and specificity." (PMID 37455827, 2023). "Additionally, to assess the ability of the listed haptoglobin N-glycopeptides to differentiate between cirrhosis and early HCC, the relative abundance of the glycopeptides was compared between the cirrhosis and HCC TNM 1 samples." (PMID 34436504, 2021). "Our data beside the mentioned previous studies shows that although haptoglobin may be introduced as a fibrosis marker, the isoforms may show a different panel for deregulation in advanced HCV-cirrhosis." (PMID 33585012, 2020). "Moreover, SAA1 and HP, which were found to be upregulated DEPs in our results, play important roles in the surveillance of HCC in patients with an early stage of cirrhosis." (PMID 31906950, 2020). "Our data shows that total haptoglobin is unreliable as a fibrosis marker since both alpha and beta chains do not consistently decrease in cirrhosis." (PMID 22761838, 2012). "However, little is known about the specific effect of cirrhosis progression on haptoglobin function, and there are few to no studies that have investigated haptoglobin and its modifications as a predictor of future decompensation events." (PMID 39521382, 2024). "Furthermore, the 2-DE profile for cirrhosis patient 5 looks different to the other gels since, unlike the other cirrhotic samples, this patient had very low levels of haptoglobin." (PMID 22761838, 2012).
gastric cancer (15 papers, 2012 to 2025). A primary or metastatic malignant neoplasm involving the stomach. "It has been found that glycosylation of haptoglobin is highly associated with gastric cancer, especially the glycosite Asn241." (PMID 34207451, 2021). "The most convincing evidence comes from a recent report on a collection of eight cohorts from China, Japan, and Korea (1447 cases and 1801 controls), in which HP-NAP seropositivity placed subjects at a 1.45 (1.26-1.68) fold magnified risk for gastric cancer." (PMID 27677314, 2017). "In this context, identification of new HP molecular virulence markers to predict gastric cancer risk will be very important." (PMID 22235308, 2012). "Gastritis (n=58) and gastric cancer (n=31) patients were evaluated and compared with H. pylori-positive asymptomatic controls (n=46), for serum antibodies against recombinant HP-NAP and IL-4 C-590T single nucleotide polymorphism using immunoblotting and PCR-RFLP, respectively." (PMID 27677314, 2017). "This study suggested that N-glycan variation of serum haptoglobin were associated with patients with gastric cancer and might be a promising marker for the cancer screening." (PMID 28052004, 2017). "In addition, potential biomarkers were classified into three groups according to the peptide sequence to determine the biological association between haptoglobin glycosylation heterogeneity and gastric cancer, indicating that the glycosite Asn241 is more closely related." (PMID 34207451, 2021). "In addition, the biological association between specific glycosylation sites of haptoglobin and gastric cancer could be identified through glycopeptide grouping." (PMID 34207451, 2021). "Such an HP-NAP-based ELISA has already been applied either to detect serum antibodies against HP-NAP in H. pylori-infected patients or to study the association of anti-HP-NAP antibody response with gastric cancer and with anti-aquaporin-4 autoimmunity related neural damage." (PMID 23577158, 2013). "In this study, we developed a new middle-up-down glycoproteome platform that can quickly and accurately monitor the abnormal glycosylation on the target glycoprotein, haptoglobin, for the diagnosis of gastric cancer." (PMID 34207451, 2021). "It was reported that miR-490-3p levels decreased gradually in the progressive changes from gastritis to IM to HP-negative and were the lowest in HP-positive gastric cancer subjects." (PMID 34071181, 2021). "Recent studies have shown that aberrant glycosylation of serum haptoglobin is closely related to gastric cancer and has enormous potential for use in diagnosis." (PMID 34207451, 2021). "We collected gastric cancer and paracarcinoma tissue samples from 50 patients and divided the samples into HP+ (all CagA+) and HP− groups." (PMID 31423013, 2019). "Our findings, from a case-control study in Iran, demonstrated that subjects with serum antibodies against HP-NAP were at higher risk of developing gastric inflammation (4.6 fold) and to a greater extent, gastric cancer (9.1 fold)." (PMID 27677314, 2017). "Based on our previous studies, differential analysis of N-glycan expression bound on serum haptoglobin reveals the quantitative variation on gastric cancer patients." (PMID 28052004, 2017). "Thus, BRD2 disrupts the homeostasis of the FLP/Caspase-8 homeostasis and regulates apoptosis and apoptosis in HP-positive gastric cancer cells." (PMID 39744419, 2025). "Haptoglobin glycosylation in clinical samples consisting of healthy controls (n = 47) and gastric cancer patients (n = 43) was extensively investigated using three groups of tryptic glycopeptides: GP1 (including Asn184), GP2 (including Asn207 and Asn211), and GP3 (including Asn241)." (PMID 34207451, 2021). "Interestingly, recent studies clearly suggest that there is an overt correlation between aberrant glycosylation of haptoglobin and gastric cancer through glycomic and glycoproteomic approaches." (PMID 34207451, 2021).
gastric cancer (continued). "Although incidence rates and mortality of gastric cancer are steadily decreasing with improved nutritional compositions and anti-HP antibody used, this disease still poses a huge threat to human health, leading to a poor diagnosis and prognosis for GC patients." (PMID 31428168, 2019). "In this study we have sequenced cagC (HP0546), cagL (HP0539) from the pilus, cagV (HP0530), cagT (HP0533), and cag Gamma (HP0523) from the core complex, and cagE (HP0544) from the energy supply enzymes from HP strains isolated from gastritis and gastric cancer patients." (PMID 22235308, 2012). "The screening of gastric cancer using the ABC classification is a method that stratifies the risk of developing gastric cancer by combining serum pepsinogen (PG) values, which are serum markers of atrophic gastritis, and anti-H. pylori IgG antibody (HP) values." (PMID 38473395, 2024).
Hypertension (15 papers, 2014 to 2025). The presence of chronic increased pressure in the systemic arterial system. "High circulating HP protein as result of gene duplication (HP2) has been associated with metabolic syndrome, high blood pressure, and elevated glucose and this could be possible explanation of the association of the HP polymorphism with T2DM risk." (PMID 27030821, 2015). "In addition, free Hb has been shown to induce hypertension, which was prevented by haptoglobin, which trap and remove hemoglobin from circulation." (PMID 33328561, 2020). "We also evaluated the effect of these polymorphisms on the incidences of T2DM related complications and hypertension which may be expected as variable circulating levels of HP and IL-1Ra in different genotypes may affect the oxidative and inflammatory status in the body." (PMID 27030821, 2015).
iron deficiency (15 papers, 2020 to 2025). "The primary function of haptoglobin is to bind haemoglobin released from erythrocytes during haemolysis, to prevent iron deficiency as well as the toxic effects of free haemoglobin." (PMID 40076444, 2025). "The present results were limited by the absence of adjustments on confounding factors associated with serum haptoglobin levels, such as haptoglobin polymorphism, inflammatory bowel disease, hemolysis, iron deficiency, and exercise." (PMID 35327501, 2022). "From a genetic point of view, some studies have indicated that the polymorphism of the haptoglobin (Hp) gene could potentially influence the interplay among dietary factors, nutrient metabolism, and the susceptibility to nutritional disorders." (PMID 38613027, 2024). "Shortened RBC age was observed in patients who were receiving maintenance haemodialysis and was associated with iron deficiency, greater haptoglobin consumption, higher ESA requirements, and poor erythropoietin responsiveness, as well as with greater intradialytic fluid extraction." (PMID 32993543, 2020). "Iron deficiency and increased haemolysis became evident, as demonstrated by borderline increased plasma cell-free Hb concentrations and reduced plasma haptoglobin." (PMID 32533377, 2020). "Therefore, we analyzed the expression of the heme transporter haptoglobin in iron deficiency." (PMID 37373063, 2023). "Moreover, the Spearman correlation coefficient revealed that shortened RBC age was associated with iron deficiency, greater haptoglobin consumption, higher ESA requirements, and poor ESA responsiveness, as well as with higher intradialytic ultrafiltration rate." (PMID 32993543, 2020). "In short-term iron deficiency, FKN increased both haptoglobin transcription and secretion, supporting our hypothesis." (PMID 37373063, 2023). "Upregulation of haptoglobin (HP) and haptoglobin-related protein (HPR), both of which bind free hemoglobin for hepatic heme iron recycling, occurred in UC but not CD, and this may represent a compensatory response to selectively minimize iron deficiency in UC but not CD." (PMID 40244226, 2025).